TRPM7 (transient receptor potential cation channel subfamily M member 7)
Diseases named in the same sentence as TRPM7 in open-access papers (continued):
Sharing a sentence is not in itself a finding about the gene and the disease.
ischemic disease (1 paper, 2020). Lack of blood supply to an area of the body, resulting in impairment of tissue oxygenation. "Consequentially, TRPM7 plays a causative role in tumorigenesis, ischemic diseases (both heart and brain), and neurodegenerative disorders." (PMID 33381038, 2020).
kidney cancer (1 paper, 2023). Primary or metastatic malignant neoplasm involving the kidney. "There have also been recent studies that Rg3 can regulate kidney cancer by blockading of TRPM7 channel activity." (PMID 36814491, 2023). "Studies have said that ginsenoside Rd can regulate kidney cancer by inhibiting TRPM7 channel activity." (PMID 36814491, 2023).
Kidney Cyst (1 paper, 2015). Abnormal fluid filled sac within the kidney, either acquired or congenital. "Deletion of TRPM7 from mouse kidney leads to kidney cysts and a defect in nephrogenesis." (PMID 26671672, 2015).
liver inflammation (1 paper, 2023). "Our results highlight the importance of the macrophage RIPK3-mediated XBP1–Foxo1–Zc3h15 signalling as a critical regulator of the NOD1 and calcineurin/TRPM7 function in IR-triggered liver inflammation." (PMID 37841640, 2023). "Here, we identify a novel regulatory mechanism of macrophage RIPK3 on NOD1 function and the TRPM7-mediated cell death pathway in IR stress-induced liver inflammation." (PMID 37841640, 2023).
mastitis (1 paper, 2020). Inflammation of breast tissue during lactation or postpartum due to an obstructed duct or infection. "Based on the conclusions of these studies, it is expected that the localization of TRPM7 in normal canine mammary glands would be a basis for studying the expression pattern of TRPM7 under pathologic conditions including mastitis and mammary gland tumor." (PMID 32168794, 2020).
multiple myeloma (1 paper, 2024). "The knockdown or inhibition of TRPM7 inhibited myeloma cell migration and dissemination." (PMID 38255793, 2024). "TRPM7 has been shown to be upregulated in myeloma cells compared with normal plasma cells." (PMID 38255793, 2024).
nasopharyngeal (1 paper, 2014). "- Required for cell growth and proliferation. - Required for migration of nasopharyngeal carcinomacells (5-8F and 6-10B). - Proliferation of FaDu hypopharyngeal squamous cells (FaDu) inhibited by midazolam that targets TRPM7." (PMID 25079291, 2014).
Neurodevelopmental delay (1 paper, 2024). "Based on the small cohort described so far, neurodevelopmental delay seems to be more prevalent in TRPM7-related disorders compared with HSH, also indicated by the presence of ASD in all three cases described here." (PMID 39099563, 2024).
oral cancer (1 paper, 2022). "Using the GSE26549 oral cancer cohort (n = 49), we also demonstrated mild or strong positive correlations between TRPM7 and NANOG (r = 0.214, p = 0.048) or BMI-1 (r = 0.628, p < 0.001)." (PMID 35771152, 2022).
pancreatic neuroendocrine tumor (1 paper, 2015). Pancreatic endocrine tumor, also known as pancreatic neuroendocrine tumor (PNET), describes a group of endocrine tumors originating in the pancreas that are usually indolent and benign, but may have the potential to be malignant. "In pancreatic neuroendocrine tumors, moderate to high expression of TRPM7 was identified." (PMID 25770184, 2015).
pancreatitis (1 paper, 2022). Inflammation of the pancreas. "Thus, it is tempting to speculate that TRPM7 could be involved in the initial PSC activation leading to pancreatitis, which is a one of the major risks for pancreatic carcinogenesis." (PMID 35883700, 2022).
peritonitis (1 paper, 2024). Inflammation of the peritoneum (tissue that lines the abdominal wall and covers most of the organs in the abdomen). "Previously, we showed that a myeloid-specific knockout of TRPM7 (Trpm7fl/fl LysM Cre) reduced systemic peripheral inflammation in a mouse model of LPS-induced peritonitis." (PMID 37943249, 2024).
pheochromocytoma (1 paper, 2021). "In pheochromocytoma cells, TRPM7 promotes production of ROS, which exert significant effects on cell survival and proliferation." (PMID 33927631, 2021).
Renal atrophy (1 paper, 2020). Atrophy of the kidney. "Indeed, using the TRPM7 inhibitor NS8593 suppressed TRPM7 expression and cell proliferation both in tubular epithelial cells and interstitial cells, prevented upregulation of Smad2/Smad3 signaling, and attenuated renal atrophy and fibrosis." (PMID 32047249, 2020).
septic shock (1 paper, 2023). Shock caused by infection; frequently caused by gram negative bacteria, although some cases have been caused by other bacteria, viruses, fungi, and protozoa; characterized by fever, chills, tachycardia, tachypnea, and hypotension. "Interestingly, circulating ECs (CECs) from septic shock patients (SSPs) showed increased TRPM7 expression associated with increased DIC scores and decreased survival times." (PMID 36869357, 2023). "Interestingly, circulating mature endothelial cells (CMECs) and circulating endothelial progenitor cells (CEPCs) from septic shock patients (SSPs) showed increased TRPM7 expression, which was associated with increased DIC scores and decreased survival times." (PMID 36869357, 2023). "To study the participation of TRPM7 in septic shock patients and its association with DIC, we performed experiments in blood samples from 25 healthy volunteers (HVs) and 22 septic shock patients (SSPs)." (PMID 36869357, 2023).
Spina bifida occulta (1 paper, 2023). The closed form of spina bifida with incomplete closure of a vertebral body with intact overlying skin. "In mice, homozygous deletion of Trpm7 is embryonic lethal, and Trpm6 knockout mutants exhibit exencephaly and/or spina bifida occulta." (PMID 37377737, 2023).
Splenomegaly (1 paper, 2018). Abnormal increased size of the spleen. "Future studies will address the cause of splenomegaly and “hyperactivated” phenotype of T cells in KD mice in addition to the mechanism through which TRPM7 kinase regulates T-cell activation process." (PMID 29445164, 2018). "TRPM7 kinase-dead (KD) K1646R knock-in mice exhibited splenomegaly and impaired blastogenic responses elicited by PMA/ionomycin or anti-CD3/CD28 antibodies." (PMID 29445164, 2018).
Stillbirth (1 paper, 2020). Death of the fetus in utero after at least 22 weeks of gestation. "In this study, we present data from previously sequenced and predicted damaging TRPM7 genetic variants found in unexplained stillbirth cases." (PMID 31423533, 2020). "TRPM7 variants found in the unexplained stillbirth population adversely affect ion channel function and this may precipitate fatal arrhythmia in utero." (PMID 31423533, 2020). "Our data indicate that inherited or de novo TRPM7 mutations may increase the risk of unexplained stillbirth and this warrants further attention." (PMID 31423533, 2020).
Testicular torsion (1 paper, 2024). Testicular torsion is when the spermatic cord to a testicle twists, cutting off the blood supply. "Others have reported that TRPM7 is activated when stimulated by ROS35, and we found increased mitochondrial superoxide in resident macrophages 24 h after testicular torsion and decreased mitochondrial membrane potential compared to the control group." (PMID 38459012, 2024).
thyroid cancer (1 paper, 2020). "Indeed, TRPM2, TRPM7, TRPM8, TRPV2, and TRPC1 have shown to cause upregulation of MMP9 in a Ca2+-dependent manner in gastric, bladder, oral squamous, prostate and thyroid cancer cells respectively." (PMID 33132914, 2020). "Additionally, TRPM2, TRPM7, and TRPC1 activity have been also correlated with MMP2 production in gastric, lung, pancreatic and thyroid cancer." (PMID 33132914, 2020).
tongue SCC (1 paper, 2022). "Our analysis of several GEO datasets (GSE12452, GSE2109, and GSE9844) showed that TRPM7 mRNA expression was upregulated in HNSCC, including NPC, tongue SCC, and hypopharyngeal SCC; high TRPM7 expression was associated with poor prognosis in HNSCC patients." (PMID 35771152, 2022).
uterine cancer (1 paper, 2024). Primary or metastatic malignant neoplasm involving the uterine corpus and/or the cervix. "Role of the TRPM7 chanzyme in the pathophysiology of ovarian and uterine cancer." (PMID 38255793, 2024).
cancer (128 papers, 2012 to 2026). A tumor composed of atypical neoplastic, often pleomorphic cells that invade other tissues. "Overexpression of TRPM7 has been linked to the development of various diseases, particularly cancers, making it a promising molecular target." (PMID 42305666, 2026). "High TRPM7 expression correlates with an increased risk of invasive and metastatic disease in many cancer types, including breast, pancreatic, bladder, gastric, ovarian, and colorectal cancer." (PMID 40003994, 2025). "We also describe the important role of TRPM7 in cancer development and cardiovascular diseases, and the interaction between TRPM7 and RTKs, providing insights for possible mechanisms underlying cardiovascular disease in cancer patients treated with RTKI/TKIs." (PMID 36818331, 2023). "We provide preclinical evidence that TRPM7 overexpression is associated with cisplatin resistance, and that shRNA-mediated TRPM7 silencing synergistically enhances cisplatin cytotoxicity of cancer cells." (PMID 35771152, 2022). "TRPM7 expression is up-regulated in many cancers as malignant behaviors of cancer cells, and its deficiency suppresses their growth." (PMID 36363540, 2022). "The most accredited Mg influx channel involved in cancer is the transient receptor potential melastatin subfamily member 7 (TRPM7), which seems to be linked to tumour growth and metastasis on various types of cancer." (PMID 33923883, 2021). "TRPM7 regulation of intracellular Ca2+ homeostasis was proposed to associate with cancer development." (PMID 33435261, 2021). "In particular, future studies on TRPM7 should evaluate not only protein expression, but also its genetic mutations and polymorphisms, that have already been found in various types of carcinoma." (PMID 33923883, 2021). "Recently, TRPM7 has been reported to be implicated in carcinogenesis and has been considered as a potential target for diverse cancer treatment." (PMID 32907556, 2020). "Expression of TRPM7 in these cancers was associated with increased expression of proliferative markers." (PMID 30995736, 2019). "The findings of over-expression of TRPM7 protein and genetic mutations/polymorphisms in the TRPM7 gene in (pre)malignant diseases suggest the potential of exploiting it as a cancer biomarker." (PMID 28379203, 2017). "The aberrant expression of TRPM7 and its genetic mutations/polymorphisms in malignant tumors suggest the opportunity for developing it as a clinical biomarker for prevention and early detection of cancer." (PMID 28379203, 2017). "The aberrant expression of TRPM7 and its genetic mutations/polymorphisms have been identified in various types of carcinoma." (PMID 28379203, 2017). "Additional studies implicate TRPM7 in tumor growth: the channel is abundantly expressed in a variety of human carcinoma cells and TRPM7 deficiency suppresses their growth." (PMID 28810912, 2017). "Despite the increasing number of studies on the role of TRPM7 in cancer, data that support the association between TRPM7 expression levels and disease progression in patients are limited." (PMID 25797249, 2015). "The goal of this article is to review the molecular, cellular, and developmental biology of the transient receptor potential melastatin-subfamily member 7 (TRPM7) channel-kinase, as well as its implicated roles in cancer." (PMID 25079291, 2014). "TRPM7 has been implicated in numerous diseases, including cancer." (PMID 41395111, 2025). "Besides the central role of TRPM7 in physiological functions, it is also linked to pathological processes such as oncogenesis, cancer progression, tumor cell survival and metastasis." (PMID 38255793, 2024). "Increased TRPM7 expression was associated with enhanced cancer stem-like and metastatic phenotypes." (PMID 38255793, 2024).
cancer (continued). "Other studies show that TRPM7 has potential to be a biomarker in pre-malignant states, as it has been shown to be overexpressed in early stages of various cancers and also shown to contain genetic mutations/polymorphisms in cancers." (PMID 37445615, 2023). "Finally, the analysis of TCGA database showed the overexpression of TRPM7 in cancer-associated fibroblasts." (PMID 35883700, 2022). "TRPM7 has been implicated in regulating myosin II-based cellular tension and focal adhesions in cancer cells in a polarized fashion as well, arguing that the polarized TRPM7-mediated Ca2+ pulses at the front of the cell are responsible for regulating cellular tension." (PMID 34069353, 2021). "Ca2+ mediated by TRPM7 is associated with a variety of diseases such as heart disease and cancer." (PMID 32643506, 2020). "Increased expression levels of TRPM7 have been associated with poor prognosis in several cancers." (PMID 28810912, 2017). "The findings of TRPM7 genetic polymorphisms and mutations in various carcinoma will be presented." (PMID 28379203, 2017). "Deregulation or dysfunction of TRPM7 is associated with a number of pathologies, including cancer." (PMID 25797249, 2015). "Thus, Glu-1052, Asp-1054, and Asp-1059 provide the binding sites for protons, and these results are important for understanding the role of TRPM7 in pathophysiological conditions associated with acidic pH, such as inflammation, ischemia, and cancer." (PMID 25079291, 2014). "Furthermore, the overexpression of TRPM7 was also observed in cancer-associated fibroblasts." (PMID 38255793, 2024). "Furthermore, TRPM7 expression is positively correlated with several clinicopathological factors associated with the poor prognosis of several cancers; hence, this protein may represent a viable therapeutic target or biomarker for tumors." (PMID 34285910, 2021). "Moreover, TRPM7 is associated with neuronal cell death under ischemic stresses and cancer invasion." (PMID 26558702, 2015). "Fibroblasts have higher levels of TRPM7 relative to HT-1080 cells and TRPM7 overexpression suppresses cancer cell intravasation in vivo." (PMID 41323575, 2025). "Several TRP family members including TRPC1/3/6, TRPV1/2/4/6, and TRPM7/8 are dysregulated during cancer progression, contributing to diverse oncogenic processes." (PMID 40806720, 2025). "In cancer and endothelial cells, TRPM7 is essential for cellular glycolysis regulation through CREB-dependent pathway." (PMID 41395111, 2025). "The mutation rates of different MHGs varied widely across cancer tissues, with ANK3 having the highest mutation rate (47%), followed by KEL (18%), TRPM7 (16%), KCNA1 (13%), CNNM2 (9%), CNNM1 (9%), TFAP2B (9%), CNNM4 (9%), XK (7%), and EDN3 (5%)." (PMID 41174507, 2025). "Studies have shown that the overexpression of TRPC6 and TRPM7 correlates with more aggressive cancer phenotypes, as they help cancer cells adapt to the stressful tumor microenvironment by maintaining calcium homeostasis." (PMID 39768254, 2024). "In patients with androgen-independent PCa, TRPM7 enhances hypoxia-induced malignant migration and invasion of cancer cells by impeding the degradation of HIF-1α mediated by the receptor for Activated C Kinase 1 (RACK1)." (PMID 39633507, 2024). "Cross‐referencing these datasets identifies NCX1, TRPC1, TRPC5, TRPM7, TRPM8, TRPML3, ORAI1/STIM1 and IP3R1 as cancer‐associated Ca2+ transporters regulated by S‐acylation via known enzyme(s)." (PMID 39429488, 2024). "Experimental data show that the increased expression and/or function of TRPM7 are observed in most malignant tumor types." (PMID 38255793, 2024). "We also describe the important role of TRPM7 in cancer development and cardiovascular diseases, and the interaction between TRPM7 and RTKs, providing insights for possible mechanisms whereby anti-cancer drugs targeting RTKs induce cardiovascular toxicity." (PMID 36818331, 2023).
cancer (continued). "Having demonstrated TRPM7 as a regulator of cancer cell glycolysis, we further characterized this channel in healthy VECs that are analogous to cancer cells in cellular metabolism." (PMID 36878949, 2023). "In this review, we summarize the implications of RTK inhibitors (RTKIs) and TKIs in cardiovascular toxicities during anti-cancer treatment, with a focus on the potential role of TRPM7/Mg2+ as a mediator of RTKI/TKI-induced cardiovascular toxicity." (PMID 36818331, 2023). "Overexpression of TRPM7 has been observed in several cancers and other disease states, and both the ion channel properties, as well as the kinase domain, are suspected of contributing through multimodal mechanisms." (PMID 36768856, 2023). "OIP5-AS1/CD147/TRPM7 axis reduces GC cell proliferation by regulating apoptosis associated with PI3K-AKT signaling, further affecting cancer metastasis." (PMID 38156103, 2023). "The results showed that the positive expression of OIP5-AS1, CD147 and TRPM7 in cancer tissues was higher than that in adjacent tissues." (PMID 38156103, 2023). "The data offer novel insights into regulation of cellular glycolysis by ion channel, and suggest that the TRPM7 channel is an exploitable target for cancer therapy and pathological neovascularization." (PMID 36878949, 2023). "In these cancer cells, O-GlcNAc is regulated by Transient receptor potential melastatin 7 (TRPM7), a cation channel that is highly expressed in cancer." (PMID 37838167, 2023). "In various cancer cells, TRPM7 was shown to positively regulate proliferation, progression, and cell invasion." (PMID 37445615, 2023). "TRPM6 has a tissue-specific expression and it is downregulated in several cancer types, while TRPM7 is ubiquitously expressed and mostly upregulated in different malignancies, where it plays a key role in promoting different cancer hallmarks." (PMID 35806388, 2022). "More big data analysis is needed to elucidate the clinical significance of TRPM7 in various types of cancers." (PMID 36363540, 2022). "First, in a TCGA cohort of HNSCC, TRPM7 is highly expressed in cancer tissues, especially the expression in invasive cancer tissues is statistically significant (p>0.001)." (PMID 35771152, 2022). "TRP channels implicated in mechanotransduction mechanisms that regulate cancer cell migration, invasion and metastasis include, among others, TRPC1, TRPC5, TRPM2, TRPM7, TRPM4, TRPV2 and TRPV4." (PMID 36158191, 2022). "TRP channels have strong implications in cancer cell migration and invasion, particularly TRPM7, which is a member of the melastatin-related TRP family, and it has been found to be upregulated in GBM." (PMID 36497413, 2022). "TRPM7 plays a variety of functional roles in the hallmarks of cancer, including survival, cell cycle progression, proliferation, migration, and invasion." (PMID 36230965, 2022). "In a panel of cancer and regular cell lines, as well as in xenograft and melanoma lung-metastasis animal models, the autophagy inhibition mediated by TRPM7 activated cell death and blocked cancel cells’ metastasis in vitro." (PMID 36844925, 2022). "The results should provide a strong rationale for developing therapeutic strategies based on candidate molecules involved in TRPM7 regulation to overcome chemoresistance in cancer cells." (PMID 35771152, 2022). "On one hand, TRPM7 overexpression enhances cancer cell migration via myosin II-based contractility, however, TRPM7 downregulation is required during intravasation to de-sensitize cells to shear stress." (PMID 36158191, 2022). "TRPM7 can also participate in cancer cell adhesion and migration via myosin-IIA filament and the MAPK signaling pathways." (PMID 36064388, 2022). "More and more data also show that TRPM7 has potential value as a molecular biomarker and therapeutic target for human malignant tumors." (PMID 36230965, 2022). "Studies have revealed the oncogenic role and therapeutic targeting of TRPM7 in different cancer types." (PMID 35771152, 2022).